SIRT6 (sirtuin 6)
Diseases named in the same sentence as SIRT6 in open-access papers (continued):
Sharing a sentence is not in itself a finding about the gene and the disease.
tumor (continued). "However, the function of SIRT6 as a tumor suppressor is still controversial, especially in the context of different tumor types, contexts, and/or stages." (PMID 39955062, 2025). "Increasing evidence has further shown that SIRT6 has a two-sided effect on tumor progression." (PMID 39845013, 2025). "Our findings elucidate the mechanisms underlying the role of SIRT6 in ccRCC by identifying an endogenous metabolite, LPE18:1, as a novel upstream activator of SIRT6 and by elucidating ACAT2 as a key downstream effector responsible for SIRT6-mediated lipid accumulation and tumor progression." (PMID 41354870, 2025). "Importantly, targeted silencing of SIRT6 via engineered exosomes carrying siRNA significantly impairs tumor growth and metastasis in preclinical models, underscoring its therapeutic relevance." (PMID 41463311, 2025). "In the context of Sirt6 ablation in the liver, glycolysis and TG synthesis were enhanced which may facilitate tumor formation." (PMID 38332150, 2024). "Since previous work indicated that lactate could strengthen anti-tumor immunity by increasing CD8+ T cells in multiple tumor models, more immunological assays were warranted to confirm the associations between SIRT6/UHRF1 and immune evasion in BLCA." (PMID 39709438, 2024). "Likewise, SIRT6 and SIRT7 have been shown to promote tumor progression, with elevated expression linked to aggressive disease and poor survival, solidifying their potential as reliable biomarkers." (PMID 39796040, 2024). "The results of this study show that SIRT6 expression is increased in CSCC tumor tissues compared to normal skin tissues, suggesting that high expression of SIRT6 may be involved in the occurrence and development of CSCC." (PMID 38548549, 2024). "Secondly, due to the complexity of tumor regulation and development, the specific mechanisms are still subject to further investigation, and subsequent in vivo experiments should be conducted to explore the impact of SIRT6 on the biological behavior of CSCC." (PMID 38548549, 2024). "In conclusion, the capacity of SIRT6 to function as a tumor suppressor, particularly through its modulation of pathways such as Lin28b, highlights its therapeutic promise for specific PDAC subtypes that rely on these epigenetic mechanisms for growth and survival." (PMID 39682281, 2024). "These previous findings indicate that SIRT6 is closely related to the development of tumor." (PMID 38819446, 2024). "This study provides clear and direct evidence that Sirt6 acts as a tumor suppressor in the liver." (PMID 38332150, 2024). "Therefore, SIRT6 also plays a role in inhibiting the initiation and development of malignant tumors, with strong heterogeneity in different tumor types." (PMID 38548549, 2024). "However, the role of SIRT6 in tumor progression is still unclear as SIRT6 can act either as a tumor promoter or tumor suppressor depending on the status of the tumor tissue." (PMID 39342193, 2024). "Importantly, overexpression of SIRT6 effectively counteracted the inhibitory effect mediated by miR-34a-5p in cSCC cells.Our findings suggest that miR-34a-5p functions as a tumor suppressor in cSCC cells by targeting SIRT6." (PMID 38819446, 2024). "However, the tumour suppression effect of SIRT6 in NSCLC was controversial, and little is known about its function in the Warburg effect in NSCLC." (PMID 39224032, 2024). "Most data support a role for SIRT6 as a tumor suppressor, but some evidence suggests that SIRT6 may promote tumor survival in an environmentally dependent manner." (PMID 39479446, 2024).
tumor (continued). "In addition, the top significant hallmark for these genes is “epithelial to mesenchymal transition” (EMT) which is consistent with the increased metastasis and mobility/invasion of SIRT6-OE tumor cells." (PMID 38081972, 2023). "By stimulating ERK1/2 activation and keeping low phospho-MAPK-p38 (pMAPK-p38) levels, Delta16HER2/SIRT6-OE tumor cells may acquire an initial proliferative advantage which later results in multiple tumor foci in vivo." (PMID 38081972, 2023). "Consequently, MDL-800 inhibits HCC cells’ proliferation through cell-cycle arrest driven by SIRT6 and shows antitumor activity in mice tumor xenograft models." (PMID 38203666, 2023). "The downregulation of SIRT6 has been shown to promote tumor development and invasiveness in vivo." (PMID 38203666, 2023). "Due to the role of SIRT6 in the regulation of DNA repair, mounting evidence points towards SIRT6 may be a target of tumor chemotherapy drug resistance." (PMID 37542062, 2023). "This evidence strengthens the concept of a context-dependent pro- or anti-tumor effect of SIRT6." (PMID 38081972, 2023). "Among the sirtuins, SIRT6 has a dual role in tumorigenesis and tumor suppression." (PMID 38235110, 2023). "Interestingly, Delta16HER2/SIRT6-OE female mice exhibit a significantly delayed tumor onset when compared to Delta16HER2 littermates." (PMID 38081972, 2023). "Sirt6 overexpression reduced tumor growth in a xenograft mouse model." (PMID 36831330, 2023). "This review aims to summarize the role of SIRT6 in carcinogenesis and tumor development." (PMID 38203666, 2023). "However, starting at 20 weeks of age, Delta16HER2/SIRT6-OE group starts to suffer from an increasing number of tumor lesions, but smaller in size with respect to Delta16HER2 controls." (PMID 38081972, 2023). "Considering the key regulating role of SIRT6 on oxidative stress in transformed cells, SIRT6 might be a potential target for countering Nrf2/Keap-mediated cellular rescue pathways in tumor cells." (PMID 38235110, 2023). "However, why this time/age-dependent effect of SIRT6 on tumorigenesis applies only to some tumor subtypes remains to be clarified." (PMID 38081972, 2023). "Indeed, even if SIRT6-OE significantly postponed tumor onset in Delta16HER2/SIRT6-OE mice, around the 20th week of age Delta16HER2/SIRT6-OE animals started to develop more tumor masses." (PMID 38081972, 2023). "In this regard, SIRT6 co-factors or targets may contribute to the different outcomes observed in different tumor types/subtypes." (PMID 38081972, 2023). "As tumor cells need to reprogram their metabolism continuously through different stages of cancer progression, we focused on the metabolic alterations manifested by SIRT6." (PMID 35686673, 2022). "Accumulating evidence has suggested that SIRT3 and SIRT6 could be served as the tumor suppressors, thus, the abnormal sirtuin status might be also responsible for the different clinical outcomes among three ECM-based clusters." (PMID 36311789, 2022). "However, some reports SIRT6 as a tumor suppressor that regulates tumor formation and maintenance of cancer." (PMID 35840633, 2022). "However, another study found that SIRT6 was an important tumor suppressor in pancreatic ductal adenocarcinoma." (PMID 35463332, 2022). "In vivo experiments also confirmed that the suppression of SIRT6 inhibits tumor growth." (PMID 35463332, 2022). "However, studies have shown that E2F promotes tumor growth by suppressing SIRT6 transcription to enhance glycolysis." (PMID 35463332, 2022). "Compared to the control group, the PC9/SIRT6 group showed significantly higher tumor volumes." (PMID 35915188, 2022). "Although our study and previous studies have revealed the significant role of MOF in tumor progression through modulating the expression of various genes, such as SIRT6 and TNK2, more studies are needed to comprehensively understand the function and complex regulatory mechanism of MOF in the future." (PMID 35252011, 2022).
tumor (continued). "Presently, the role of SIRT6 in a variety of diseases is yet disputable, and some scholars maintain that it is a tumor suppressor modulating the occurrence and advancement of multiple tumor diseases." (PMID 36159576, 2022). "At present, few studies have shown whether SIRT6 could enhance the anti-tumor ability by regulating the activity of immune cells; this may become a new research direction in the future." (PMID 35463332, 2022). "SIRT6 being a “metabolic sensor” fosters metabolic changes conducive to tumor growth." (PMID 35686673, 2022). "However, there is quite a consensus in the literature that HDAC4, HDAC7, HDAC9, SIRT2, and SIRT7 are upregulated in GC and seem to be pro-tumor factors, whereas SIRT4, SIRT5, and SIRT6, which are downregulated, seem to have a tumor suppressor function." (PMID 36358890, 2022). "SIRT6, a member of the sirtuin family, is closely related to tumorigenesis and tumor development; however, whether SIRT6 promotes or inhibits tumor growth remains controversial." (PMID 35915188, 2022). "Taken together, our results define SIRT6-dependent glucose metabolism reprogramming as an early event during tumorigenesis, promoting tumor initiation by increasing the number of cells that can give rise to a tumor." (PMID 35314684, 2022). "In addition, immunohistochemical analysis showed that the expression of SIRT6, HIF-1α, HK2 and Ki-67 in tumor tissues of the PC9/SIRT6 group was higher than that of the PC9/vector group." (PMID 35915188, 2022). "This study shows that, similar to SIRT4 and SIRT5, SIRT6 expression is lower in GC tissue when compared to normal gastric tissue, and that its decreased expression correlates with tumor grade, tumor size, and TNM stage, along with decreased overall survival and DFS of GC patients." (PMID 36358890, 2022). "The role of SIRT6 in tumour promotion has been extensively studied in recent years." (PMID 35172823, 2022). "SIRT6 expression levels vary significantly between tumour types." (PMID 35172823, 2022). "By contrast, tumor-suppressive roles for SIRT6 in HCC models have also been reported." (PMID 35890276, 2022). "However, not only SIRT1 but also NAD-dependent protein deacetylase sirtuin-6 (SIRT6), which simultaneously plays a role as a tumor suppressor and oncogene, can be phosphorylated by CK2." (PMID 36009534, 2022). "In particular, SIRT6 is a core member of the sirtuin family that is involved in regulating various biological processes, such as glycolysis, glutamine metabolism and fatty acid metabolism of tumor cells." (PMID 35915188, 2022). "Previous works indicated that SIRT6 plays a relevant role in aging biochemical functions involved in tumor progression and could constitute an antitumor therapeutic target." (PMID 35136826, 2022). "In addition, another mechanism by which SIRT6 is proposed to act as a tumour suppressor is by defatty‐acylation of lysine in R‐RAS2, a member of Ras family of GTPases, frequently implicated in human cancers." (PMID 34212132, 2021). "Studies have also reported tumor-promoting activity of SIRT6." (PMID 33920726, 2021). "However, another study showed that SIRT1, SIRT3, and SIRT6 function as the tumor suppressors in RCC." (PMID 34778292, 2021). "Given the reported tumor suppressor activity of SIRT6, it is attractive to imagine compounds that could selectively activate SIRT6 through interactions with the hydrophobic groove." (PMID 34368168, 2021). "Besides, SIRT6 modulation has been suggested to play a pivotal role in the tumor microenvironment of various cancers." (PMID 33920726, 2021). "In vivo tumor growth of KHOS/NP cells was also significantly decreased with the transfection of the SIRT6-S338A mutant compared with the overexpression of WT-CSNK2A1 or WT-CSNK2A1/WT-SIRT6." (PMID 34359939, 2021).
tumor (continued). "Given that GLUT4 is an insulin‐responsive glucose transporter, the increased GLUT4 level seen in our tumour model could be either because of the direct effect of SIRT6 on Glut4 promoter or a consequence of increased plasma insulin levels or both." (PMID 34212132, 2021). "In addition, overexpression of SIRT6 worsened the survival status in tumor-bearing mice, accompanied by short overall survival and decreased body weight." (PMID 33995674, 2021). "Several studies showed that NB metastatic cells express distinctive features from primary tumor cells, including down-regulation of several tumor suppressor genes (i.e., SIRT6, BBC3/PUMA, STK11, CADM4 and GLTSCR2) and up-regulation of immunosuppressive molecules, such as calprotectin and HLA-G." (PMID 33921337, 2021). "We then describe the most promising modulators of SIRT6 which, through enzyme activation or inhibition, may impair tumor growth." (PMID 33800266, 2021). "Recently, emerging studies have uncovered the tumor-promoting function of SIRT6." (PMID 33995674, 2021). "SIRT6 has been extensively reported to modulate tumor progression." (PMID 34225779, 2021). "As a tumor promoter, SIRT6 promotes cell cycle and tumor proliferation while inhibiting apoptosis." (PMID 34650436, 2021). "Findings of these experiments suggest that SIRT6 by targeting the inhibitor WNT4 might modulate insulin secretion from pancreatic β‐cells and thereby probably curtail muscle atrophy associated with tumour growth in Tu‐Sk.T6Tg mice." (PMID 34212132, 2021). "SIRT6 is overexpressed in some cancers and SIRT6 inhibition may have tumor suppressive effects in these cases, but also SIRT6 activation can induce anti-cancer activities in SIRT6 deficient cancers." (PMID 33684691, 2021). "Therefore, SIRT6 shows a dichotomous role in cancer, acting both as tumor promoter and suppressor in a cell context-dependent fashion." (PMID 33800266, 2021). "The xenografted tumor sections from these two groups were processed to detect the proliferation rate of cells by immunofluorescence staining with an anti-Ki67 antibody, and increased cell proliferation rate in SIRT6-OE group was evident." (PMID 33995674, 2021). "FoxO3a is a tumor suppressor involved in the positive regulation of apoptosis, in the protection against oxidative stress, and also in the cholesterol biosynthesis regulation along with SIRT6." (PMID 33800266, 2021). "Among the seven SIRTs, SIRT1, SIRT3, and SIRT6 can be used as tumor suppressors in KIRC." (PMID 34194607, 2021). "In cancers, SIRT6 is also viewed both as a tumor promoter and a tumor suppressor." (PMID 34650436, 2021). "Therefore, it is vital to distinguish thepotential of SIRT6 as a therapeutic target or as a biomarker in eachtype of tumor." (PMID 34213345, 2021). "In our study, we find that SIRT6 over‐expression could restore insulin secretion to normal levels in tumour‐bearing mice." (PMID 34212132, 2021). "SIRT6 expression was elevated by LA in murine tumor tissues." (PMID 34702956, 2021). "We assume that fluvastatin possess an anti-tumor potential in EC by SIRT6." (PMID 34927546, 2021). "But also tumor promoting effects of Sirt6 have been described." (PMID 32426286, 2020). "Thus, functional SIRT6 attends to the upkeep of myriad pathways that maintain metabolism and tumor suppression." (PMID 33067423, 2020). "Xenografted DLBCL tissues grown from shSirt6 cells possessed lower rates of cells that stained positive for Ki-67 in comparison to cells that had endogenous levels of Sirt6, indicating that Sirt6 inhibition may have tumor suppressive effects." (PMID 32711549, 2020). "Furthermore, we established a mouse xenograft model using human DLBCL cells to investigate the tumor-promoting effect of Sirt6 in vivo." (PMID 32711549, 2020).
tumor (continued). "As alluded to above, there is controversy regarding the role of Sirt6 in tumor development." (PMID 32711549, 2020). "SIRT6 overexpression significantly inhibited tumor growth compared with the NC." (PMID 32983963, 2020). "SIRT6 displays dual functions in tumorigenesis acting as tumor suppressor or promoter." (PMID 32488123, 2020). "Recently, the role of SIRT6 in tumor development has been partly studied." (PMID 33335996, 2020). "However, in tumor cells such as colon cancer cells, SIRT6 binds directly to the hypoxia-responsive elements of the glycometabolism genes and blocks HIF-1α-induced glycometabolism without activating oncogenic pathway." (PMID 33109235, 2020). "However, the effect of the anti-tumor effect of doxorubicin was attenuated by overexpression of SIRT6." (PMID 33198792, 2020). "In response to DNA damage induced by UV irradiation, SIRT6 may exert a tumor-suppressive function by stabilizing the genome through upregulating NER." (PMID 32789493, 2020). "However, there are controversial reports on the role of SIRT6 in tumorigenesis and tumor progression." (PMID 33198792, 2020). "Thus activation of Sirt6 controls tumor growth and metastasis by regulating the overexpression of HIF1α." (PMID 33442387, 2020). "Sirt6 expression levels may modulate DNA damage, thereby affecting tumor resistance to DNA damage agents." (PMID 32711549, 2020). "SIRT6 is closely related to chromatin, deacetylates H3K9 and H3K56, and regulates glucose metabolism, inflammation, gene expression, and genomic stability, which is associated with tumor survival." (PMID 33335996, 2020). "However, due to its dual role in cancer as both tumor suppressor and oncogene, the identification of conditions able to control SIRT6 regarding cancer prevention and treatment is challenging." (PMID 32488123, 2020). "Furthermore, knock-down of SIRT6 significantly potentiated the inhibitory effect of doxorubicin on in vivo tumor growth." (PMID 33198792, 2020). "The inhibition of c-Fos by c-Jun in early tumor stages blocks SIRT6 expression." (PMID 31591350, 2019). "SIRT6 is involved in inflammatory, aging, and tumor processes in the body." (PMID 31477582, 2019). "Similar to other sirtuins, SIRT6 also plays a role in tumor suppression or progression." (PMID 31817470, 2019). "Moreover, overexpression of SIRT6 and SIRT7 was associated with tumor stage II and a better outcome." (PMID 31572453, 2019). "Targeting the anti-apoptotic activity of survivin at the initiation stage (or increase of the levels of SIRT6) may compromise the development of cancer which may be used as an approach against tumor set-up and age-related diseases." (PMID 31591350, 2019). "Interestingly, SIRT6 is well-known for its tumour suppressor roles and it has been shown to be downregulated or mutated in multiple cancer types." (PMID 31372634, 2019). "Furthermore, the effect of NQO1 and SIRT6 on tumor growth was determined in cell model and orthotopic tumor implantation model." (PMID 31842909, 2019). "Similarly, SIRT6 involvement in tumorigenesis is tissue-context specific, and displays both functions of tumor promoter and tumor suppressor." (PMID 30761005, 2019). "Moreover, it is reported that overexpression of SIRT6 results in increased ROS production and that a specific miR-33a by suppressing SIRT6 induced tumor growth through oxidative stress resistance." (PMID 30250025, 2018). "All of these results taken together demonstrate the importance of SIRT6 in tumor progression." (PMID 29966233, 2018). "Indeed, SIRT6 was reported as tumour suppressor in pancreatic cancer, as well as other isoforms in different tumours." (PMID 30356832, 2018). "In some tumors, SIRT6 acts as a tumor suppressor; indeed, SIRT6 expression has been found downregulated in many human tumors (i.e. colorectal, breast, ovarian, hepatocellular, lung, and pancreatic tumors) and its downregulation is associated with poor prognosis." (PMID 30250025, 2018).